MIR33B (microRNA 33b)
Synonyms: hsa-mir-33b; MIRN33B; mir-33b
Gene: MicroRNA gene on chromosome 17 (17,813,836 to 17,813,931, reverse strand). Ensembl gene ENSG00000207839.
Gene Ontology:
Biological process: miRNA-mediated post-transcriptional gene silencing
Cellular component: RISC complex
Homologues: Orthologues: chimpanzee ptr-mir-33b (100% identical), macaque mml-mir-33b (99% identical), guinea pig MIR33B (69% identical), Drosophila melanogaster mir-33 (47% identical), tropical clawed frog xtr-mir-33a (47% identical). Paralogues in human: MIR33A (48% identical).